FAT4 (FAT atypical cadherin 4)
Description:
Cadherins are calcium-dependent cell adhesion proteins. FAT4 plays a role in the maintenance of planar cell polarity as well as in inhibition of YAP1-mediated neuroprogenitor cell proliferation and differentiation (By similarity).
Synonyms: CDHF14; FATJ; Nbla00548; FAT-J; CDHR11; HKLLS2; VMLDS2
Tractability: Antibody: UniProt predicts a signal peptide or a membrane-spanning region; its Gene Ontology location is reachable by antibodies, with medium confidence. PROTAC: ubiquitination databases record sites on it; its protein half-life has been measured.
Gene: Protein-coding gene on chromosome 4 (125,314,918 to 125,492,932, forward strand). Ensembl gene ENSG00000196159.
Subcellular location: Membrane
Subcellular location (Human Protein Atlas): Cytosol
Gene Ontology:
Molecular function: protein binding; calcium ion binding
Biological process: axonogenesis; cell-cell adhesion mediated by cadherin; cerebral cortex development; epithelial cell differentiation; heterophilic cell-cell adhesion; hippo signaling; neurogenesis; cell adhesion; cell-cell adhesion; epithelium development; generation of neurons; homophilic cell-cell adhesion
Cellular component: extracellular exosome; adherens junction; plasma membrane; membrane
Genetic constraint (gnomAD): Loss-of-function variants: 79 observed, 300.79 expected, observed/expected ratio (o/e) 0.26, 90% interval 0.22 to 0.32. The upper end of that interval is the gene's LOEUF score, 0.32, which puts it in group 1 of 6, group 1 being the genes least tolerant of losing a copy. Missense variants: 5,900 observed, 6,368.2 expected, observed/expected ratio (o/e) 0.93, 90% interval 0.91 to 0.95. Synonymous variants: 2,273 observed, 2,394.7 expected, observed/expected ratio (o/e) 0.95, 90% interval 0.92 to 0.98.
Gene-disease validity (ClinGen):
ClinGen rates the evidence that FAT4 causes each of these diseases.
FAT4-related neurodevelopmental disorder (autosomal recessive): Definitive. Any neurodevelopmental disorder, frequently presenting with lymphatic dysplasia, craniofacial and limb anomalies, and secondary lymphopenia from altered immune cell trafficking, in which the cause of the disease is a variation in the FAT4 gene.
Cancer hallmarks: suppression of growth (promotes); invasion and metastasis (suppresses)
Homologues: Orthologues: chimpanzee FAT4 (99% identical), macaque FAT4 (99% identical), rabbit FAT4 (95% identical), pig FAT4 (94% identical), rat Fat4 (92% identical), mouse Fat4 (91% identical), guinea pig FAT4 (91% identical), tropical clawed frog fat4 (76% identical), zebrafish FAT4 (64% identical), Drosophila melanogaster ft (37% identical). Paralogues in human: FAT3 (25% identical), FAT1 (25% identical), FAT2 (22% identical), CELSR1 (11% identical), CELSR3 (11% identical), CELSR2 (10% identical).
Diseases named in the same sentence as FAT4 in open-access papers:
FAT4 is named in the same sentence as 110 diseases in open-access papers, as found by Europe PMC text mining. Sharing a sentence is not in itself a finding about the gene and the disease. The quoted sentences say what the papers report.
gastric cancer (29 papers, 2012 to 2026). A primary or metastatic malignant neoplasm involving the stomach. "High FAT4 expression was associated with a favorable prognosis in colorectal cancer and gastric cancer." (PMID 36811800, 2023). "FAT4 was reported to modulate the nuclear translocation of β-catenin to facilitate the transcription of Wnt target genes in gastric cancer 33, but the underlying mechanism was unclear." (PMID 31695775, 2019). "Non-synonymous FAT4 mutations are detected in 2 out of 15 cases of gastric cancers using the whole-exome approach and in 4 out of additional 95 cases of gastric cancers using the candidate-exon approach." (PMID 23076869, 2012). "FAT4 is mutated in several types of human cancer, such as melanoma, pancreatic cancer and gastric cancer." (PMID 23076869, 2012). "FAT4 gene is recurrently mutated in several types of human cancers, such as melanoma, pancreatic cancer, gastric cancer and hepatocellular carcinoma." (PMID 23076869, 2012). "Increasing evidence suggests that the downregulation of FAT4 may be associated with the progression of several malignant carcinomas, including breast cancer, colorectal cancer, and gastric cancer." (PMID 35770846, 2023). "In addition, a prevalence screening confirmed mutations in FAT4 in 5% of gastric cancers, but the specific mechanism was still unclear." (PMID 36051999, 2022). "Tumour microarrays (TMAs) were used to analyse the expression of UBE4B and FAT4 in the tumour and adjacent normal tissues of 94 patients with gastric cancer, as well as the corresponding clinicopathological information." (PMID 40701960, 2025). "The bioconfidence analysis revealed that FAT4 was expressed at significantly lower levels in gastric cancer tissues from patients than in normal gastric mucosal tissues." (PMID 40701960, 2025). "In this study, we identified the interaction of the U-box structural domain in UBE4B with FAT4 as an important molecular mechanism that regulates gastric cancer progression." (PMID 40701960, 2025). "Here, our findings reveal a novel mechanism by which UBE4B mediates the ubiquitination and degradation of FAT4 to promote gastric cancer progression." (PMID 40701960, 2025). "This ubiquitination-mediated downregulation of FAT4 expression promotes gastric cancer cell proliferation, migration and invasion in gastric cancer cells." (PMID 40701960, 2025). "FAT4 mutation is frequent and associated with higher TMB in gastric cancer, leading to an anti-tumor immune response." (PMID 39323626, 2024). "Previous findings also proved FAT4 inhibits proliferation and metastasis in breast cancer, endometrial cancer, and gastric cancer cell lines." (PMID 35770846, 2023). "Studies have also shown that the tumor-suppressive functions of FAT4 were also identified in breast and gastric cancers." (PMID 36051999, 2022). "FAT4, a cadherin-related protein, was shown to function as a tumour suppressor in gastric cancer by modulating Wnt/β-catenin signaling." (PMID 33836681, 2021). "A study indicated that FAT4 has a low expression in gastric cancer and is targeted by miR-107, which results in activation of PI3K/AKT signaling and causes the promotion of gastric cancer growth and metastasis." (PMID 33063118, 2020). "There is increasing evidence of a possible relation between the FAT4 downregulation and the pathogenesis of several malignancies, including breast, colorectal, and gastric cancers." (PMID 32366234, 2020). "It was reported that expression of FAT4 is low-expressed in gastric cancer, endometrial cancer and hepatocellular carcinoma." (PMID 33063118, 2020). "FAT4 can increase the expression levels of constituents of this complex by subsequently downregulating both T-β-catenin and N-β-catenin expression in gastric cancer." (PMID 30832706, 2019). "For example, GATA2 was suggested as a prospective indicator for poor prognosis in patients with colorectal cancer, and FAT4 functions as a tumor suppressor for stomach cancer." (PMID 29299064, 2017).
gastric cancer (continued). "Among the human FAT gene family, FAT4 gene is recurrently mutated in several types of human cancers, such as melanoma (40%), pancreatic cancer (8%), HNSCC (6%) and gastric cancer (5%)." (PMID 23076869, 2012). "This growth inhibition could be reversed by FAT4 knockdown, suggesting that the regulation of gastric cancer by UBE4B depends on FAT4." (PMID 40701960, 2025). "In addition, downregulation of FAT4 is correlated with lymph node metastasis and poor prognosis in endometrial cancer and gastric cancer." (PMID 35770846, 2023). "Furthermore, silencing of FAT4 stimulated proliferation, migration, and cell cycle progression in gastric cancer by modulating YAP nuclear translocation." (PMID 35770846, 2023). "miR-107 promotes the growth and metastasis of gastric cancer via activation of PI3K-AKT signaling pathway by targeting FAT4, which may be a target for gastric cancer treatment." (PMID 36051999, 2022). "The inhibition of EMT by FAT4 may be mediated by levels of β-catenin followed by downregulation of Twist1 expression, as confirmed in a previous gastric cancer study." (PMID 35132327, 2022). "In this study, FAT4 repression increased cyclin D1, and cdk4 expression, promoting progression into the G1/S phase of the cell cycle, consistent with results obtained in a previous study on gastric cancer cells." (PMID 32366234, 2020). "Moreover, in gastric cancer, FAT4 silencing stimulated cell proliferation, migration, and cell cycle progression through the nuclear translocation of YAP." (PMID 32366234, 2020). "However, FAT4, which is reduced in bile from these patients, is a cadherin-related protein identified as a tumor suppressor in gastric cancer." (PMID 32575903, 2020). "Moreover, exome sequencing of FAT4 in gastric cancer revealed hyper-methylation of the FAT4 promoter, suggesting that epigenetics is a likely mechanism behind FAT4 downregulation." (PMID 32366234, 2020). "FAT4 is a 543-kD protein and usually acts as a tumor suppressor 16; it was reported to be involved in Wnt/β-catenin signaling by modulating β-catenin nuclear translocation in gastric cancer." (PMID 31695775, 2019). "The potential tumor suppressive role of FAT4 was reported in breast and gastric cancers." (PMID 26672766, 2016). "Moreover, FAT4 knockdown has been shown to induce the malignant phenotype of human gastric cancer cell lines." (PMID 25679223, 2015). "FAT4 encodes a cadherin-related protein in the FAT family playing the role of tumor suppressor through Hippo and Wnt/β-catenin signaling pathways, recurrent mutations of which were reported in multiple cancer types, such as gastric cancer, myeloma, and endometrial cancer." (PMID 36811800, 2023). "Similarly, a previous finding revealed that FAT4 knocked-down gastric cancer cells displayed higher levels of nuclear β-catenin accumulation as compared to the cytosolic fraction, thereby increasing cell growth over 6 days, while β-catenin repression reduced the growth." (PMID 32366234, 2020). "Furthermore, FAT4 silencing promoted metastasis in vivo, in gastric cancer xenograft mouse model." (PMID 32366234, 2020). "Furthermore, the function of FAT4 in gastric cancer was previously studied." (PMID 30832706, 2019). "In this study, we investigated the role of Fat atypical cadherin 4 (FAT4) in gastric cancer (GC) progression." (PMID 29435168, 2018). "Driver genes in gastric cancer, such as CDH1 and FAT4, were present in area D2, and genes involved in cell adhesion were enriched." (PMID 31829249, 2019). "Indeed, FAT4 has been shown to have an important role in inhibiting EMT and human gastric cancer cell proliferation." (PMID 37735184, 2023). "FAT4 functions as a tumor suppressor, and previous findings have demonstrated that FAT4 can inhibit the epithelial-to-mesenchymal transition (EMT) and the proliferation of gastric cancer cells." (PMID 30832706, 2019).
gastric cancer (continued). "We also found six genes in MSS tumors (EYS, FAT4, FSIP2, PCDHA1, RAD50, and RECQL4) and two in MSI tumors (EXO1 and FSIP2) that were clonally mutated in multiple patients and have not been previously identified as drivers of gastric cancer or other cancers." (PMID 36970058, 2022). "In addition, FAT4 might decrease the levels of β-catenin and then downregulate Twist1 expression to suppress CRC development, as demonstrated in the study of gastric cancer conducted by Cai." (PMID 30832706, 2019).
colorectal cancer (23 papers, 2015 to 2025). A primary or metastatic malignant neoplasm that affects the colon or rectum. "Recurrent mutations of FAT4 were detected in several human cancers, such as melanoma and colorectal cancer." (PMID 26672766, 2016). "Similarly, mutations in FAT4 have been reported in various malignancies, including melanoma, colorectal carcinoma, and esophageal carcinoma." (PMID 39235515, 2025). "Although FAT4 mutations have been described in colorectal cancers before, their role in response prediction is still unknown." (PMID 35392220, 2022). "In addition, for another gene FAT4, which is also detected by our model but not curated in benchmarking lists, the high prevalence of mutations in FAT4 are also recognized among the colorectal cancer patients." (PMID 29871594, 2018). "Recently, FAT4 was reported as a recurrently mutated driver gene in the colorectal cancer." (PMID 26590405, 2016). "Additionally, the mutational frequency was >10% in 8 other TSGs in colorectal cancer: FAT4 (19%), TOPORS (15%), PPP2CB (13%), RASL11A (13%), PCDH9 (12%), PRDM2 (12%), LIFR (11%) and TGFBR2 (11%)." (PMID 26590405, 2016). "More importantly, FAT4 promotes autophagy and inhibits the invasion, migration, and proliferation of lung and colorectal cancer cells." (PMID 40701960, 2025). "It has been shown to influence the migration and invasion of colorectal cancer cells by targeting FAT4, with overexpression of miR-106b-5p promoting these processes." (PMID 41155295, 2025). "Meanwhile, in colorectal cancer, FAT4 has been found to regulate PI3K activity in the PI3K/AKT/mTOR signaling pathway, inhibit tumor growth, and contribute to preventing EMT25." (PMID 37735184, 2023). "In colorectal cancer, it was found that FAT4 regulated the PI3K/AKT/mTOR signaling pathway through modulating PI3K activity, preventing EMT, and inhibiting tumorigenesis." (PMID 35770846, 2023). "While in colorectal cancer, FAT4 was found to inhibit tumorigenesis by regulating the PI3K activity in the PI3K/AKT/mTOR signaling pathway and to play a significant role in preventing the epithelial-to-mesenchymal transition (EMT)." (PMID 32366234, 2020). "In this study, FAT4 was identified as a putative cancer gene involved in lung and colorectal cancer, which is consistent with previous studies." (PMID 26352260, 2015). "Notably, in lung and colorectal cancers, the by which FAT4 inhibits tumour growth is closely related to the regulation of tumour autophagy." (PMID 40701960, 2025). "However, few studies have investigated the role of FAT4 in the development of colorectal cancer (CRC)." (PMID 30832706, 2019). "The opposing effects of miR-106b-5p on migration and invasion in colorectal cancer, depending on whether it targets FAT4 or CTSA, underscore the complexity of miRNA function and the possibility that different regulatory networks become dominant in different stages or subtypes of colorectal cancer." (PMID 41155295, 2025). "FAT4 mutation could predict survival outcomes for stratifying patients with colorectal cancer independent of TNM staging." (PMID 36341436, 2022). "The authors also reported that FAT4 promotes autophagy through PI3K/AKT signaling pathway to inhibit invasion and migration of colorectal cancer." (PMID 35715752, 2022). "FAT4 regulates the EMT and autophagy in colorectal cancer cells in part via the PI3K-AKT signaling axis." (PMID 35836939, 2022). "MicroRNA-106b-5p (miR-106b-5p) is involved in the development of many cancers including colorectal cancer (CRC), and FAT4 is correlated with regulation of growth and apoptosis of cancer cells." (PMID 33063118, 2020). "In line with our findings, in colorectal cancer, the downregulation of GSK-3-β upon FAT4 repression, while upregulation of its phosphorylated form, was observed, which was attributed to the PI3K-AKT pathway in colorectal cancer." (PMID 32366234, 2020).
colorectal cancer (continued). "It has been found that FAT4 (FAT tumor suppressor homolog 4) could regulate the autophagy and the EMT process in colorectal cancer cells by blocking the PI3K-Akt signaling pathway." (PMID 35677158, 2022). "Our method is able to identify the known driver genes for colorectal cancer; additionally, we also identified some driver genes not found by the MutSigCV study, such as COL12A1, MLL2, FAT4 and ARID1A." (PMID 26379039, 2015).
Hennekam syndrome (17 papers, 2019 to 2025). Hennekam syndrome is characterized by the association of lymphoedema, intestinal lymphangiectasia, intellectual deficit and facial dysmorphism. "Mutations in FAT4 have been associated with Van Maldergem syndrome and Hennekam syndrome, rare diseases with lymphedema." (PMID 40455044, 2025). "Mutations in FAT4 have been associated with Hennekam syndrome, a genetically diverse condition characterized by lymphedema, lymphatic vessel dilatation, and mental retardation, emphasizing the critical role of FAT4 in the lymphovascular system." (PMID 38430054, 2024). "Another protein-coding gene associated with Van Maldergem Syndrome 2 and Hennekam Lymphangiectasia–Lymphedema Syndrome 2 is the FAT4 gene (FAT Atypical Cadherin 4), which is involved in approximately 20% of Hennekam syndrome cases." (PMID 37322437, 2023). "Diagnosis of VMLDS is complicated, especially regarding its similarity of symptoms to Hennekam syndrome, another disorder caused by FAT4 variants." (PMID 37551355, 2022). "In particular, heterozygous loss-of-function mutations in CELSR1 are correlated with Lymphatic malformation 9 (OMIM: 619319), while homozygous mutations in FAT4 are correlated with Hennekam lymphangiectasia-lymphedema syndrome 2 (OMIM: 616006)." (PMID 35806420, 2022). "FAT4 mutations in humans are associated with Hennekam syndrome, a rare congenital disease characterized by lymphedema, while loss of Fat4 in mouse prevents perpendicular rearrangement of LvECs without affecting specification." (PMID 34716915, 2021). "Mutations in FAT4 are linked to Hennekam syndrome, while biallelic mutations in FAT4 or DCHS1 genes are associated with Van Maldergem syndrome (VMS)." (PMID 33108146, 2020). "FAT4 mutations associated with malignancy are mainly attributed to somatic variants, whereas germline FAT4 variants have only been associated with Hennekam syndrome and van Maldergem syndrome, with their contributions to autoinflammatory phenotypes unknown." (PMID 39492681, 2025). "Notably, mutations in the atypical calcineurin protein FAT4 have been identified in patients with Hennekam syndrome, which is characterized by lymphedema as one of its features." (PMID 40766782, 2025). "Mutations in Fat4 and DCHS1 are associated with Van Maldergem and Hennekam syndrome and many cancers." (PMID 35372364, 2022). "Almost 25% of patient's diseases are influenced by biallelic mutations in CCBE1 (Hennekam lymphangiectasia-lymphedema syndrome 1 (HKLLS1; MIM: 235510)) and FAT4 (Hennekam lymphangiectasia-lymphedema syndrome 2 (HKLLS2; MIM: 616006)) while CCBE 1 gene mutation." (PMID 34234628, 2021). "Similarly, FAT4 and DCHS1 mutations in Hennekam syndrome and Van Maldergem syndrome patients, two genetic diseases that involve developmental defects in cell migration, are believed to cause a loss of function." (PMID 39478125, 2024). "Mutations in FAT4 and DCHS1 are associated with many cancers and multi system developmental defects such as Van Maldergem syndrome and Hennekam syndrome, characterized by craniofacial anomalies, intellectual dysfunction, digital contractures, hypoplastic kidneys, sternal and auditory defects." (PMID 35372364, 2022). "HKLLS1 (Hennekam lymphangiectasia-lymphedema syndrome 1, OMIM #235510) can be caused by mutation of FAT4, and in addition to lymphedema may also present with camptodactyly or syndactyly, digit aberrations common in ciliopathies." (PMID 34055805, 2021). "Finally, patients with Hennekam syndrome, resulting from mutations in CCBE1, FAT4 or ADAMTS3, exhibit diffuse lymphatic dysplasia which also affects lymph flow in the gut." (PMID 33147779, 2020). "This is in line with the observation that recessive mutations in FAT4 result in Van Maldergem syndrome (MIM615546) and Hennekam lymphangiectasia-lymphedema syndrome 2 (MIM616006), neither of which include coloboma or any other eye defects." (PMID 30862798, 2019).